ANKRD34A (ankyrin repeat domain 34A)
Synonyms: ANKRD34
Tractability: PROTAC: its protein half-life has been measured.
Gene: Protein-coding gene on chromosome 1 (145,959,441 to 145,964,575, reverse strand). Ensembl gene ENSG00000272031.
Subcellular location (Human Protein Atlas): Cytosol
Gene Ontology:
Cellular component: cytosol; pi-body
Genetic constraint (gnomAD): Loss-of-function variants: 7 observed, 28.11 expected, observed/expected ratio (o/e) 0.25, 90% interval 0.14 to 0.47. The upper end of that interval is the gene's LOEUF score, 0.47, which puts it in group 2 of 6, group 1 being the genes least tolerant of losing a copy. Missense variants: 472 observed, 697.97 expected, observed/expected ratio (o/e) 0.68, 90% interval 0.63 to 0.73. Synonymous variants: 299 observed, 308.88 expected, observed/expected ratio (o/e) 0.97, 90% interval 0.88 to 1.07.
Homologues: Orthologues: chimpanzee ANKRD34A (99% identical), macaque ANKRD34A (99% identical), dog ANKRD34A (97% identical), rabbit ANKRD34A (97% identical), pig ANKRD34A (97% identical), mouse Ankrd34a (97% identical), rat Ankrd34a (96% identical), guinea pig ANKRD34A (96% identical), tropical clawed frog ankrd34a (61% identical). Paralogues in human: ANKRD34B (36% identical).
Diseases named in the same sentence as ANKRD34A in open-access papers:
ANKRD34A is named in the same sentence as 5 diseases in open-access papers, as found by Europe PMC text mining. Sharing a sentence is not in itself a finding about the gene and the disease. The quoted sentences say what the papers report.
glioma (1 paper, 2020). A benign or malignant brain and spinal cord tumor that arises from glial cells (astrocytes, oligodendrocytes, ependymal cells). "Therefore, it is reasonable for us to connect the methylation status of ANKRD34A with glioma." (PMID 33329750, 2020).
ANKRD34A also shares sentences with these, for which no sentence is quoted: tumor (2 papers); cancer (1); lymphoma (1); ovarian carcinoma (1).